NLRP3 (NLR family pyrin domain containing 3)
Diseases named in the same sentence as NLRP3 in open-access papers (continued):
Sharing a sentence is not in itself a finding about the gene and the disease.
gastric cancer (continued). "Besides, it was found that lncRNA ADAMTS9-AS2 was significantly reduced in gastric cancer, thus inhibiting the development of gastric cancer via miRNA-223-3p/NLRP3 axis." (PMID 34907204, 2021). "Furthermore, mycoplasma hyorhinis-induced activation of the NLRP3 inflammasome has been shown to promote gastric cancer metastasis." (PMID 34457117, 2021). "The role of NLRP3 activity was also analyzed in gastric cancer." (PMID 32796686, 2020). "The inhibition of IL-1β after pSTAT3 inhibition by WP1066 is particularly significant, because IL-1β is an important regulator of gastric acid secretion, a potent promoter of tumour growth in a transgenic mouse model of gastric cancer, and an integral part of the NLRP3 inflammasome." (PMID 24804649, 2014). "Our data suggest that activation of the NLRP3 inflammasome by M.hy may be associated with its promotion of gastric cancer metastasis, and anti-M.hy therapy or limiting NLRP3 signaling could be effective approach for control of gastric cancer progress." (PMID 24223129, 2013). "The regulation of NLRP3 may be a potential tool to control tumor development due to the inhibitory effect of NLRP3 on the progression and development of cancer cells in liver cancer and gastric cancer." (PMID 37705746, 2023). "Here, we investigated the prognostic value of the NLR family pyrin domain containing (NLRP) 1/NLRP3 inflammasome and its potential mechanisms in immune-regulation in gastric cancer (GC)." (PMID 36541912, 2022). "Additionally, Helicobacter pylori infection enhances NLRP3 expression and subsequent inflammasome activation and IL-1β release in macrophages, which could enhance the tumorigenesis of gastric cancer." (PMID 35990696, 2022). "LncRNA ADAMTS9-AS2 activated pyroptosis cell death mediated by NLRP3 through sponging miR-223-3p to increase the sensitivity of cisplatin in gastric cancer (GC) to inhibit tumor development." (PMID 35223836, 2022). "Therefore, NLRP3 by a combination of dependent and independent inflammasome pathways may increase proliferation of gastric cancer cells and GC development." (PMID 30447690, 2018). "However, whether M.hy, which is an important factor in gastric cancer development activates the NLRP3 inflammasome and whether this activation contributes to the gastric cancer development remain unknown." (PMID 24223129, 2013). "In gastric cancer, RBPMS2 is overexpressed, predicts poor prognosis, and promotes proliferation, invasion, and migration by suppressing NLRP3/caspase-1/GSDMD-mediated pyroptosis." (PMID 41562091, 2025). "In gastric cancer (GC), the activation of pyroptosis-related genes (PRGs) such as GSDMD and GSDME is linked to favorable prognosis, while agents like famotidine, simvastatin, icariin, and diosbulbin-B trigger NLRP3 or caspase-3-mediated pyroptosis." (PMID 40806716, 2025). "In gastric cancer, LncRNA ADAMTS9-AS2 activates NLRP3-mediated pyroptosis by adsorbing miR-223-3p, thereby serving as a tumor suppressor and enhancing cisplatin sensitivity." (PMID 38697992, 2024). "For example, quercetin induces pyroptosis in gastric cancer cells by increasing the expression of pyroptosis markers such as GSDMD, GSDME, and NLRP3 in a concentration-dependent manner." (PMID 39584140, 2024). "Wang and colleagues showed that NLRP3 mediates small mother against the decapentaplegic (SMAD) signaling pathway which, in turn, downregulates E-cadherin and promotes the EMT in gastric cancer cells." (PMID 37891577, 2023). "Thus, the NLRP3 inflammasome promotes gastric cancer and its downregulation by the activity of the aryl hydrocarbon receptor (AhR), dopamine receptor D1 (DRD1) and G protein-coupled bile acid receptor 1, (GPBAR1) may limit the occurrence of pyroptosis, thereby affecting cancer progression." (PMID 37081882, 2023).
gastric cancer (continued). "Chrysophanol has been shown to promote MKN28 gastric cancer cell pyroptosis via NLRP3/Caspase1/GSDMD, and the Caspase1 inhibitor VX765 can reduce the chrysophanol-induced pyroptosis of MKN28 gastric cancer cells." (PMID 36105214, 2022). "In gastric cancer, lncRNA ADAMTS9-AS2 not only suppressed tumor cell but also increased chemosensitivity of cisplatin through pyroptosis mediated by NLRP3." (PMID 36618967, 2022). "Furthermore, in a gastric cancer (GC) model, NLRP3 promoted CyclinD1 gene (CCND1) transcription, enhancing GC proliferation and tumorigenesis." (PMID 35745570, 2022). "The ability of NLRP3 to bind to the CCND1 promoter and to support its transcription was already described in gastric cancer." (PMID 35745570, 2022). "As already demonstrated for gastric cancer, miR-22 suppresses growth, migration and invasion in OSCC cells by affecting the functions of the NLRP3 inflammasome." (PMID 34064909, 2021). "Most important, both NLRP3 and GSDMD expression were increased in gastric cancer tissue of patients with H. pylori infectious." (PMID 34266494, 2021). "Herein, we further showed that famotidine stimulation in gastric cancer cells of BGC823 and AGS significantly promoted cell pyroptosis by inducing NLRP3 activation, leading to caspase-1 activation, IL-1β and IL-18 release." (PMID 34686215, 2021). "It was shown that NLRP3 inflammasome activation promotes gastric cancer (GC) cells proliferation." (PMID 31118894, 2019). "NLRP3, COX-2, and NF-κB p-p65 are highly expressed in the HGC-27 gastric cancer cell line." (PMID 38906903, 2024). "In addition, by downregulating PD-L1 to activate NLRP3-mediated pyroptosis, Diosbulbin B extracted from Dioscorea bulbifera L. can sensitize DDP-resistant gastric cancer cells to DDP." (PMID 38239395, 2023).
lupus nephritis (69 papers, 2015 to 2026). Glomerulonephritis in the context of systemic lupus erythematosus. "In lupus nephritis tissue, infiltration of CD68+ cells expressing NLRP3, a molecule upregulated in Mo stimulated with snRNP IC, was associated with treatment outcomes, supporting an important role for MPs in lupus nephritis." (PMID 41648138, 2026). "Research has shown that, compared to other groups, SLE patients—particularly those with lupus nephritis (LN)—exhibit increased NLRP3 inflammasome activation because of significant gain-of-function mutations in the NLRP3 gene." (PMID 40830103, 2025). "Melatonin has protective activity on lupus nephritis that is associated with its effect on enhancing antioxidant signaling and decreasing renal NLRP3 inflammasome activation." (PMID 39350252, 2024). "Our data clearly demonstrate that melatonin has protective activity on lupus nephritis in these mice that is highly associated with its effect on enhancing the Nrf2 antioxidant signaling pathway and decreasing renal NLRP3 inflammasome activation." (PMID 31311094, 2019). "Inflammatory responses were evaluated by quantifying the expression of NF-κB p65 and NLRP3 inflammasome, both pivotal in lupus nephritis pathogenesis." (PMID 41601976, 2026). "Future studies with larger cohorts, longer follow-up, and multi-omics approaches are warranted to validate these preliminary findings and to explore the mechanistic links between NLRP3 activation and treatment resistance in lupus nephritis." (PMID 41515921, 2025). "The expression of NLRP3 has been detected in podocytes of patients with lupus nephritis, along with an increase in urine protein levels." (PMID 41357229, 2025). "By modulating NLRP3 inflammasome and NF-κB signaling pathways, dioscin ameliorate kidney damage induced by lupus nephritis." (PMID 40731269, 2025). "Previous studies have reported persistent activation of TLRs and NLRP3 in diabetic kidney disease (DKD), IgAN, and lupus nephritis, while abnormalities or mutations in TRPC6 calcium channels are common in focal segmental glomerulosclerosis and DKD." (PMID 41476974, 2025). "Contributions of the P2X7R/NLRP3 pathway to renal injury have been confirmed in cases of lupus nephritis." (PMID 40520155, 2025). "Podocytes derived from renal biopsy tissues and urine samples have exhibited the expression of NLRP3, IL-1β, and caspase-1 in patients with class IV and V lupus nephritis." (PMID 38740765, 2024). "The activation of the NLRP3 inflammasome is another key pathway involved in the pathogenesis of lupus nephritis, with the subsequent production of cytokines." (PMID 37371054, 2023). "Studies have shown that the NLRP3 inflammasome is upregulated in lupus nephritis patients and that its inhibition can ameliorate kidney injury in animal models of lupus nephritis." (PMID 37371054, 2023). "The role of autophagy in regulating NLRP3 inflammasome in the podocyte injury in lupus nephritis is less explored." (PMID 35999224, 2022). "Based on previous findings, our results suggested that CD36 promotes podocyte injury by activating the NLRP3 inflammasome in lupus nephritis." (PMID 35999224, 2022). "In conclusion, our study demonstrated that CD36 promoted podocyte injury in lupus nephritis by activating the NLRP3 inflammasome and inhibiting autophagy." (PMID 35999224, 2022). "According to a new finding, activation of the NLRP3 inflammasome led to proteinuria and podocyte injury in lupus nephritis." (PMID 36248187, 2022). "BAY 11-7082, a phosphorylated NF-κB inhibitor decreased macrophage invasion by inhibiting NLRP3-inflammasome activation resulting in decreased lupus nephritis and increased mice survival." (PMID 35204131, 2022). "In vitro, CD36, NLRP3 inflammasome, and autophagy were elevated accompanied with increased podocyte injury stimulated by IgG extracted from lupus nephritis patients compared that from healthy donors." (PMID 35999224, 2022).
lupus nephritis (continued). "In lupus nephritis, activation of Nrf2 inhibits gene transcription of the NLRP3 inflammasome and inhibits the production of IL-1β, a downstream product." (PMID 35136484, 2022). "Studies have shown that the NLRP3 inflammasome is overactivated in lupus nephritis, which promotes the exacerbation of inflammation and the progression of LN." (PMID 35999224, 2022). "We observed that CD36 and NLRP3 (NLR family pyrin domain containing 3) were upregulated in the podocytes of lupus nephritis patients and MRL/lpr mice with renal impairment." (PMID 35999224, 2022). "Necroptosis mediated NLRP3 inflammasome plays a key role in the pathogenesis of lupus nephritis as well as the transition from AKI to CKD." (PMID 35204131, 2022). "Honokiol and dibenzylideneacetone (Tris) dipalladium both have potential therapeutic effect against accelerated and severe type of lupus nephritis by suppressing NLRP3 inflammasome activation." (PMID 34707607, 2021). "Cf-02 can treat acute onset of severe lupus nephritis in mice by inhibiting the NF-κB/NLRP3 inflammasome axis and regulating T cell functions differentially." (PMID 34707607, 2021). "BAY 11-7082, a phosphorylated NF-κB inhibitor (IκB), reduced macrophage infiltration and inhibited the activation of NLRP3 inflammasome, thereby alleviating lupus nephritis in mice and improving the mouse survival rate." (PMID 32410864, 2020). "MN also attenuated the NLRP3 inflammasome via inhibition of the NF-κB signaling pathway on lupus nephritis in MRL/lpr mice." (PMID 32714487, 2020). "Fu et.al also demonstrated that NZB/W F1 mice treated with pim-1 inhibitor AZD1208 showed a suppression of NLRP3 inflammasome activation and a significant reduction in the severity of lupus nephritis." (PMID 31871956, 2019). "There is a previous report that EGCG reduces the messenger RNA (mRNA) and protein expression of renal NLRP3 in a lupus nephritis mouse model." (PMID 31174271, 2019). "A recent study reported the upregulation of the NLRP3 inflammasome in podocytes in renal biopsies from patients with lupus nephritis." (PMID 31694192, 2019). "Taken together, these findings indicate that inflammasome-dependent NLRP3 in immune cells and podocytes is important for lupus nephritis progression." (PMID 31694192, 2019). "EGCG has been reported to inhibit NLRP3 inflammasome, and subsequently IL-1β expression in human umbilical vein endothelial cells exposed to palmitate, and lupus nephritis." (PMID 26866373, 2016). "In human conditionally immortalized glomerular podocytes treated with serum from MRL/lpr mice or in the kidneys of MRL/lpr mice, notable increases in and activation of NLRP3-induced pyroptosis signaling were observed, suggesting a role of podocyte pyroptosis in promoting lupus nephritis." (PMID 39850113, 2025). "In human renal biopsy tissues, including IgA nephropathy, lupus nephritis, minimal change disease, hypertensive nephropathy, and secondary focal segmental glomerulosclerosis, significantly increased expression of NLRP3 mRNA has been detected compared with normal tissues." (PMID 41357229, 2025). "Epimedium glycoside and magnolol may alleviate kidney damage in patients with lupus nephritis (LN) by modulating the NF-κB/NLRP3 pathway." (PMID 41357229, 2025). "Furthermore, RIP3-dependent activation of the NLRP3 inflammasome pathway has been found in inflammatory diseases such as lupus nephritis and early brain injury following subarachnoid hemorrhage." (PMID 38338718, 2024). "The NLRP3 inflammasome contribute to tissue damage in lupus nephritis." (PMID 37371054, 2023). "The NLRP3-inflammasomes also contribute to the pathogenesis of lupus nephritis." (PMID 35204131, 2022). "In summary, we identified the CEBPB-Pim-1 signal axis could promote the activation of NLRP3 inflammasome and pyroptosis of glomerular podocytes, which may serve as a therapeutic target against lupus nephritis." (PMID 36248187, 2022).
lupus nephritis (continued). "Moreover, in MRL/LPR animals, inhibiting NLRP3 inflammasome activity indirectly by P2 × 7 suppression and NF-κB pathway suppressed lupus nephritis." (PMID 35204131, 2022). "Another study suggested that down-regulation of BGN levels in models such as unilateral ureteral obstruction and lupus nephritis effectively reduces the expression levels of nucleotide-binding oligomerisation domain-like receptor protein 3 (NLRP3) and caspase-1 activity." (PMID 35069594, 2021). "PCB2 suppresses lupus nephritis in MRL/lpr mice by inhibiting the NLRP3 inflammasome." (PMID 32528469, 2020). "Furthermore, our findings revealed for the first time that CD36 was upregulated in podocytes from patients with lupus nephritis and might promote podocyte injury by activating the NLRP3 inflammasome." (PMID 35999224, 2022). "However, whether CD36 promotes podocyte injury by regulating the NLRP3 inflammasome in lupus nephritis remains to be established." (PMID 35999224, 2022). "In the lupus nephritis mouse model, the study found a significant increase in inflammatory molecules in the P2X7/NLRP3 signaling pathway." (PMID 41357229, 2025). "Zhao and group discovered that decreasing NLRP3 recruitment and subsequent caspase-1 activity by blocking P2 × 7R, decreased glomerular damage in MRL/LPR mice with lupus nephritis, lowering serum anti-dsDNA antibody level, as well as IL-1β and IL-17 levels." (PMID 35204131, 2022). "In our present study, we observed that upon stimulation with IgG extracted from lupus nephritis patients, CD36 was upregulated in podocytes, and NLRP3 inflammasome levels and podocyte apoptosis were increased in vitro." (PMID 35999224, 2022). "Studies have shown activation of the NLRP3 inflammasome in various CKDs, such as obstructive nephropathy, chronic type II crystalline nephropathy, DNP, lupus nephritis, and IgA nephropathy, further exacerbating kidney damage." (PMID 34671403, 2021). "A study of pristane-induced lupus nephritis in mice shows that ingested melatonin restores SIRT1 and Nrf2 protein levels, reduces NF-κB and NLRP3 levels, and reverses lesions and morphological alterations in kidneys of pristane-administered mice." (PMID 34202842, 2021). "Epigallocatechin-3-gallate prevents lupus nephritis development in mice via enhancing the NRF2 antioxidant pathway and inhibiting NLRP3 inflammasome activation." (PMID 34084175, 2021). "NLRP3 inflammasome, one of the inflammasome sensors mediating pyroptosis, was found hyperactivated in patients with SLE and lupus nephritis (LN)." (PMID 31871956, 2019). "The expression of NOD2, NLRP3 and NLRC5 was significantly higher in kidneys from AAV patients than those from normal controls, minimal change disease or class IV lupus nephritis." (PMID 31186034, 2019). "In contrast, in the kidney, the expression of genes involved in pyroptosis, e.g. NLRP3 and CASP1 were significantly increased and TNFR1, RIPK1, RIPK3, CIAP1/2 and GPX4 were significantly decreased along the progression of lupus nephritis (LN)." (PMID 27811014, 2016). "Although kidney epithelial cells do not appear to express much of NLRP3 mRNA under healthy conditions, kidney biopsies from patients with lupus nephritis showed an increase in NLRP3 expression in podocytes." (PMID 37564649, 2023). "NLRP3 inflammasome is activated in podocytes of patients with lupus nephritis and mice, and inhibition of NLRP3 by MCC950 attenuates proteinuria, renal pathological damage, and podocyte fusion in mice with lupus nephritis." (PMID 35873572, 2022). "Similarly, in the spontaneous lupus nephritis a mutant strain of NZM2328 mice with MCC950 administration showed significant inhibition in the expression of pro-caspase-1, p20 caspase-1, NLRP3 and IL-1β49." (PMID 35079027, 2022). "Moreover, in lupus nephritis, GSK3 activates NLRP3 and therefore, IL-1β production, and psychological stress activating GSK3 induces the NLRP3/IL-1β pathway." (PMID 30174579, 2018).
lupus nephritis (continued). "NLRP3/ASC promotes renal glomerular damage by increasing T cell infiltration, but mice lacking NLRP3 or ASC also develop severe lupus nephritis, which may be associated with other signaling pathways such as TGF-β." (PMID 37960237, 2023). "However, quercetin reversed the expression of NLRP3, ASC, caspase-1, N-GSDMD, and IL-1β induced by IL-33, indicating that quercetin can relieve inflammasome- and GSDMD-mediated pyroptosis in the cellular model of lupus nephritis." (PMID 36421424, 2022). "The observation and study of NZB/WF1 lupus nephritis mouse model showed that TLR7, TLR8, and TLR9 antagonists can effectively alleviate the progress of glomerular damage and interstitial inflammation while reducing the transcription levels of IL-1β and NLRP3 in the kidney." (PMID 32410864, 2020). "Compared to those in SLE patients without renal damage, patients with lupus nephritis (LN) exhibited lower mRNA levels of NEK7, NLRP3, and ASC but higher levels of Caspase-1, IL-1b, and IL-18." (PMID 30202244, 2018). "However, the researchers did not demonstrate NLRP3 inhibition, in contrast with a previous study that demonstrated the preventive effects of EGCG in lupus nephritis mice via NLRP3 inhibition." (PMID 32650482, 2020).